BAP1 (BRCA1 associated deubiquitinase 1)
Diseases named in the same sentence as BAP1 in open-access papers (continued):
Sharing a sentence is not in itself a finding about the gene and the disease.
uveal melanoma (continued). "One study showed that deep learning could be used to predict BAP1 expression status in H&E-stained uveal melanoma WSIs with near ophthalmic pathologist performance on an internal test cohort." (PMID 34441338, 2021). "We conclude that there is substantial intratumor heterogeneity in uveal melanoma BAP-1 expression." (PMID 33800007, 2021). "A nonsense mutation in the BRCA1 associated protein 1 (BAP1) gene has been reported in the post-therapy tumor of a hyperprogressive patient, and the loss of BAP1 expression was highly correlated with HIF-1α expression in uveal melanoma." (PMID 33467713, 2021). "In conclusion, there is substantial intratumor heterogeneity in uveal melanoma BAP-1 expression." (PMID 33800007, 2021). "In general, more cutaneous melanoma and ocular melanoma in the family history was reported in patients with uveal melanoma and a BAP1 germline mutation compared to patients without this germline mutation." (PMID 33396957, 2020). "BAP1 loss is frequent in MPM, renal cell carcinoma, peritoneal mesothelioma, and uveal melanoma." (PMID 32824422, 2020). "Uveal melanoma (UM) has well-characterised somatic copy number alterations (SCNA) in chromosomes 1, 3, 6 and 8, in addition to mutations in GNAQ, GNA11, CYSLTR2, PLCB4, BAP1, SF3B1 and EIF1AX, most being linked to metastatic-risk." (PMID 32340176, 2020). "Loss of BAP1 in uveal melanoma cells did not impact cell proliferation or tumorigenesis; rather, loss of BAP1 led to de-differentiation accompanied by increased stem-like biomarkers." (PMID 32028647, 2020). "Similar to somatic mutations, germline mutation of BAP1 was highly associated with metastasis as compared with uveal melanoma without BAP1 mutation." (PMID 32429485, 2020). "The frequency of BAP1 germline mutations is higher in families with cutaneous and uveal melanoma compared to families without uveal melanoma." (PMID 33396957, 2020). "Uveal melanoma (UM) remains without effective therapy at the metastatic stage, which is associated with BAP-1 (BRCA1 associated protein) mutations." (PMID 31146482, 2019). "In this study, we verified whether artificial intelligence could predict manual assessments of BAP1 expression in 47 enucleated eyes with uveal melanoma, collected from one European and one American referral center." (PMID 31623293, 2019). "In addition, the patient’s CGP demonstrated mutation of BRCA1-associated protein 1 (BAP1) gene, which is frequently inactivated in metastatic uveal melanomas." (PMID 28302097, 2017). "Alterations in BAP1 expression in other cancers such as renal cell carcinoma, breast carcinoma, small cell and non-small cell lung cancers, malignant mesothelioma, metastasizing uveal melanoma, and hepatic cancers can arise from chromosomal deletions." (PMID 28122578, 2017). "BAP1 is located at the chromosome region 3p21.1, which is a genomic region that is deleted in several human malignancies; accordingly, dysregulation of BAP1 has been reported in many types of cancers, such as uveal melanoma, meningioma and lung adenocarcinoma." (PMID 26885612, 2016). "Such a model should accurately mimic different characteristics of uveal melanoma such as genetics (monosomy 3, GNAQ/GNA11, and BAP1 mutations), hematogenous spread to the liver, (as the eye lacks lymphatics), an inflammatory tumor microenvironment, and other tumor growth characteristics." (PMID 27366747, 2016). "Furthermore, stable BAP1 depletion in a uveal melanoma cell line leads to sensitization to the HDAC inhibitor valproic acid and decreased viability." (PMID 25970771, 2015). "In subsequent studies in US families with high incidence of MM and of uveal melanoma (UM) and no apparent exposure to mineral fibers, we identified germline mutations in the BAP1 gene, as the major risk factor for MM and UM development." (PMID 26683624, 2015). "In addition, we saw consistent up-regulation of the stem cell factor NANOG in BAP1-depleted uveal melanoma cells." (PMID 23915344, 2013).
uveal melanoma (continued). "Uveal melanoma cells were studied following RNAi-mediated depletion of BAP1 using proliferation, BrdU incorporation, flow cytometry, migration, invasion, differentiation and clonogenic assays, as well as in vivo tumorigenicity experiments in NOD-SCID-Gamma mice." (PMID 23915344, 2013). "Since BRCA pathway deregulation and telomere dysfunction are both associated with amplifications and deletions in cancer cells, we wished to determine whether BAP1 depletion might result in such large-scale chromosomal gains and losses in uveal melanoma cells." (PMID 23915344, 2013). "Interestingly, BAP1 suppression in uveal melanoma cells led to a profound shift from spindled bipolar cells to more rounded epithelioid cells - a cellular phenotype consistent with the observed histopathology." (PMID 22545102, 2012). "Therefore, we focused our investigation on the novel finding of dysregulated lipid metabolism, which may contribute to the distinct clinical behavior and metastatic propensity of BAP1‐mutant uveal melanoma." (PMID 40300851, 2025). "In contrast to uveal melanomas, where BAP1 mutations serve as a significant prognostic indicator of an unfavorable outcome, BAP1 mutations in non-uveal melanomas are primarily considered passenger mutations and do not appear to be relevant from a prognostic or therapeutic perspective." (PMID 38903495, 2024). "Interestingly, three patients with BAP1 wild-type uveal melanoma had disease response, suggesting that the immunomodulatory function of HDAC inhibitors may be the predominant contributing function in anti-tumoral activity." (PMID 37370834, 2023). "Another research in uveal melanoma revealed that BAP1 could induce methylomic repatterning." (PMID 35941663, 2022). "Deletion of BAP1 could facilitate metastasis of uveal melanoma." (PMID 33397441, 2021). "Indeed, a recent comprehensive analysis of MBD4 mutations in uveal melanoma confirmed the role of MBD4 as a tumor suppressor in line with Knudson's two‐hit hypothesis, and convincingly joined BAP1 as the only identified predisposing genes for uveal melanoma." (PMID 36618446, 2021). "Interestingly, activation of the PI3K pathway was found to occur in some uveal melanomas lacking BAP1 pathogenic variants." (PMID 34533562, 2021). "Notably, it has been reported that sensitivity of uveal melanoma to EZH2 inhibitors is independent of BAP1 mutational status, suggesting a lineage-specific effect of BAP1 on the activity of EZH2i (EZH2 inhibitors)." (PMID 33072611, 2020). "Additionally, the loss of Bap1 did not enhance the aggressiveness of uveal melanomas; in fact, the ocular phenotype was weaker, and there was no increase in size or incidence of lung lesions compared with mice expressing GNA11Q209L alone." (PMID 31880399, 2020). "Consistently, results from previous studies in other types of cancer, including uveal melanoma, clear-cell renal cell carcinoma, gastric adenocarcinoma, colorectal cancer, and non-small-cell lung cancer, also documented a significant decrease in tumor BAP1 expression." (PMID 30305612, 2018). "Interestingly, morphologic changes were also observed after BAP1 expression modulation in uveal melanoma cell lines, although no loss of cellular identity was observed in our study." (PMID 29069806, 2017). "However, this is not what we found in uveal melanoma, where BAP1 loss seemed to be associated with increased HLA expression." (PMID 27764126, 2016). "However, recently, novel established permanent cell lines from primary and metastatic uveal melanomas exhibiting a characteristic genetic profile (including GNAQ, GNA11, or BAP1 mutations) allow for further investigations on genetic pathways and their influence on tumor progression and metastasis." (PMID 27366747, 2016). "However, it is currently unknown whether these LMNs harbor mutations in BAP1, SF3B1 and/or EIF1AX like uveal melanomas as well." (PMID 26769193, 2016).
uveal melanoma (continued). "This study reveals a novel mechanism linking BAP1 expression to lipid sensitivity via ASXL2, providing insights into liver tropism and potential therapeutic avenues for metastatic uveal melanoma." (PMID 40300851, 2025). "Knowing this and as we have presented, uveal melanoma patients with monosomy of chromosome 3p (implicating VHL and BAP1) and gain of chromosome 8q (PTK2) have a worse prognosis." (PMID 40000790, 2025). "Genetics and immunology will be cutting-edge research areas in uveal melanoma, with attention to genes such as GNAQ, GNA11, and BAP1, highlighted as important focus points." (PMID 39898362, 2025). "A few genes, e.g., BAP1 and MDB4, are the only established genes correlated to hereditary and syndromic forms of Uveal Melanoma (UM)." (PMID 38254993, 2024). "As a further exemplar of the value of our BAP1 SGE data, we identified a family whose proband presented at the age of 26 years with uveal melanoma." (PMID 38969833, 2024). "Major genetic drivers identified in uveal melanoma include early events activating GNAQ (at 9q21) or GNA11 (at 19p13) and later events involving EIF1AX (at Xp22) or SF3B1 (at 2q33) or BAP1 (at 3p21)." (PMID 37761808, 2023). "Some specific genes such as BAP1, EIF1AX, and SF3B1 are related to uveal melanoma metastasis and have prognostic value in UM." (PMID 34739630, 2022). "When Bap1 deletion was combined with GNA11Q209L expression, uveal melanomas were unexpectedly smaller." (PMID 31880399, 2020). "Inactivation of the BAP1 gene which codes for an enzyme that binds to BRCA1 and BARD1 in regulating the tumor suppressor complex has been described in up to 84% of class 2 uveal melanomas." (PMID 25874144, 2015). "Both cases lacked mutations in the common uveal melanoma tumor suppressors, SF3B1, BAP1, and EIF1AX." (PMID 39804140, 2025). "Taken together, these results indicate the independent role of DTYMK and PARP1 in the pathobiology of uveal melanoma, regardless of BAP1 status." (PMID 39195238, 2024). "We found that GZ17-6.02 as a single agent increased BAP1 expression in uveal melanoma cells that was not altered by ERBB receptor inhibitors." (PMID 38758815, 2024). "This study aims to further understand the role of BAP1 and its implications on clinical course in non-uveal and uveal melanoma by examining a multicenter cohort and correlating clinical and survival information in the respective patients." (PMID 38903495, 2024). "BAP1 depletion has also been shown to reduce cell proliferation through S-phase accumulation in MPM, while it is suggested to function primarily as a metastasis suppressor in uveal melanoma." (PMID 36669126, 2023). "In our study, the analysis of BAP1 in both tumour groups showed that the absence of BAP1 expression was significantly more frequent in pigmented uveal melanoma (p = 0.029)." (PMID 35681733, 2022). "Analysis of BAP1 in both tumour groups showed that the absence of immunohistochemical BAP1 expression was significantly more frequent in pigmented uveal melanoma (p = 0.029)." (PMID 35681733, 2022). "Some cases presented with mutations usually linked to uveal melanomas (GNAQ, GNA11, SF3B1, BAP1), but these mutations did not co-occur, suggesting a different tumorigenesis process than in UM." (PMID 34359736, 2021). "Depletion of BAP1, a known suppressor of metastasis in patients, increased the amount of transmigration of uveal melanoma cells in transwell assays; but BAP1 depletion did not affect the rate of intercalation, based on movies of living cells." (PMID 25506912, 2014). "However, in uveal melanoma, BAP1-mutant cells do not exhibit strong evidence of DNA damage repair defects." (PMID 40867321, 2025). "The absence of BAP1 is a significant contributor to metastasis in uveal melanoma." (PMID 38724687, 2024). "In contrast, although BAP1 loss was shown recently to induce ASS1 in malignant mesothelioma cell lines with an inverse correlation in clinical samples, the same relationship is not apparent in uveal melanoma." (PMID 35466524, 2022).
uveal melanoma (continued). "In the absence of BAP1 mutations, other gene mutations are usually present, such as SF3B1, a gene associated with late-onset metastasis and EIF1AX, associated with low-risk profile of uveal melanoma and a low risk for metastasis." (PMID 35413810, 2022). "Uveal melanoma may be the first sign of BAP1 TPDS and until today children are not routinely assessed for constitutional pathogenic BAP1 variants in Germany." (PMID 33919815, 2021). "Uveal melanoma is not the only tumor that has been related to inhibited BAP1 proteins." (PMID 34771510, 2021). "The fact that BAP1-depleted uveal melanoma cells did not exhibit a growth advantage or increased metastatic capacity in xenograft mouse models was surprising but indicates that these models are not adequate for elucidating the role of BAP1 in vivo." (PMID 23915344, 2013). "First, the histopathology slides used to train the deep learning network were from two centers, but may not fully represent either the diversity of nuclear BAP1 expression in uveal melanoma, or the spectrum of interlaboratory differences in the results of fixation, sectioning, and staining." (PMID 31623293, 2019).
melanoma (178 papers, 2012 to 2026). A malignant, usually aggressive tumor composed of atypical, neoplastic melanocytes. "Inherited BAP1 mutations cause melanoma and other cancers and can also lead to white hair patches or skin spots due to pigment cell loss." (PMID 41480773, 2026). "With DepMap, we confirm that CRISPR-mediated deletion of BAP1 in 96 melanoma lines is associated with a loss of melanoma viability." (PMID 41480773, 2026). "In contrast to the initial set of 19 BIMs, 3/5 patients with BAP1‐inactivated melanomas experienced an adverse event, and the remaining two cases had histologic features that were fully diagnostic of melanoma." (PMID 39976080, 2025). "The melanoma arising in the patient with BAP1 germline mutation showed loss of nuclear BAP1 staining but diffusely positive cytoplasmic staining, and PRAME showed focal nuclear expression." (PMID 39268598, 2025). "No individual develops both: this is inconsistent with the observed impact of BAP1 mutations on melanoma." (PMID 40597050, 2025). "Diverging from its status in melanoma and cholangiocarcinoma, where the primary genomic alteration of BAP1 occurs as a mutation, the predominant genomic alteration of BAP1 in pancreatic cancer is copy number loss (shallow deletion 26.03%, deep deletion 0.54%)." (PMID 39350280, 2024). "Among a cohort of 2650 melanoma patients, 129 patients harboring a BAP1 mutation (BAP1mut) were identified and included in this study." (PMID 38903495, 2024). "A retrospective analysis of all melanomas sequenced in our department from 2014–2022 (n=2650) was conducted to identify BAP1 mutated samples." (PMID 38903495, 2024). "In melanoma, BAP1 deficiency significantly elevated anaerobic glycolysis levels, leading to more lactate production in tumor cells." (PMID 39587076, 2024). "BAP1-mutated melanomas had distinct clinical and pathological features, including younger age at diagnosis, higher frequency of multiple primary melanomas, uveal melanoma, and a distinct gene expression profile." (PMID 37504268, 2023). "CDKN2A, CDK4, and BRCA1-associated protein 1 (BAP1) have been identified as high-risk melanoma susceptibility genes." (PMID 37504268, 2023). "BAP1 mutation, preferentially expressed antigen in melanoma (PRAME) status, and GEP class are defined from clinically indicated tumor biopsy when available." (PMID 37047796, 2023). "According to expert opinion, the transformation risk of BAP1-inactivated melanocytic nevi/tumours into melanoma is low, similar to atypical/dysplastic nevi (Clark nevi)." (PMID 37607989, 2023). "BAP1 germline variants are commonly associated with predisposition for the development of multiple cancer types including melanoma." (PMID 36883553, 2023). "In the case of sporadic melanomas, comprising more than 90% of all melanomas, several susceptibility loci acting as moderate (BAP1, TERT, POT1, ACD, TERF2IP and MITF) or low penetration genes have been identified." (PMID 36765773, 2023). "Two of them, FAMMM and BRCA1-associated protein-1 (BAP1) tumor predisposition syndrome, a malignant tumor syndrome (including melanoma) associated with the mutation of the BAP1 gene, are described in the following paragraphs." (PMID 35465855, 2022). "Zhang found that many of these tumors are associated with BAP1 mutations, compared with nodular melanoma or superficial spreading melanoma, which are associated with BRAF and NRAS mutations." (PMID 36289768, 2022). "These melanomas typically have BAP1 mutations and lack the typical genetic alterations of conventional melanoma." (PMID 36140455, 2022). "Many HR genes (BRCA1/2 and BAP1) are also related to syndromes that enhance genetic predisposition to cancer, including melanoma." (PMID 35563772, 2022).